TLR7 (toll like receptor 7)
Diseases named in the same sentence as TLR7 in open-access papers (continued):
Sharing a sentence is not in itself a finding about the gene and the disease.
breast carcinoma (continued). "However, further research is needed to fully understand the mechanisms by which TLR7 signaling can either promote or inhibit breast cancer progression and to optimize the potential therapeutic strategies targeting this pathway." (PMID 38903515, 2024). "The anti-tumor effects of TLR7 activation may depend on factors such as the dose of the agonist, the tumor microenvironment, and the breast cancer subtype." (PMID 38903515, 2024). "Therefore, the interplay between TLR8 and TLR7, as well as their combined effects on breast cancer progression and immunity, require further investigation." (PMID 38903515, 2024). "Moreover, an ongoing clinical trial aiming at evaluating the HER2-targeted TLR7/TLR8 mixed agonist ISAC BDC-1001 is enrolling individuals with HER2+ breast cancer (NCT04278144)." (PMID 37063284, 2023). "Toll-like receptor 7 (TLR7) and TLR9 (TLR9) agonist intratumoral injection increases tumor-associated monocyte infiltration and TAM phenotypic modification in a mouse model of breast cancer." (PMID 37138860, 2023). "TLR4 and TLR7 also correlated with a significantly poorer prognosis in the MetastaSys cohort, as previously demonstrated for breast cancer primaries." (PMID 36224342, 2022). "Topical TLR7 agonists including imiquimod and R848 have been shown to induce an immune response as well as promote some level of tumor control in a variety of cancer types, including melanoma and breast cancer." (PMID 32508825, 2020). "Hence, restoring the ability of tumor associated pDCs to produce IFN-α in combination with TLR7/9-based immunotherapy with TGF-β and TNF-α antagonists can restore the antitumor immunity in breast cancer patients." (PMID 32784928, 2020). "In this regard, it was noted that, apart from TLR6, TLR7, and TLR8, the expression levels of the other TLRs were lower in breast cancer tissues compared to normal tissues." (PMID 41550509, 2026). "Another study on the MDSCs isolated from breast cancer patients revealed that STAT3 inhibition and TLR7/8 pathway stimulation in MDSCs repolarize and suppress MDSCs of breast cancer patients." (PMID 36476317, 2022). "Our group developed a novel TLR7 agonist-conjugated MUC1 peptide vaccine that elicited effective immune responses and robust antitumor effects in a mouse breast cancer model." (PMID 36499455, 2022). "Consequently, TLR-3, TLR-6, TLR7/8, and TLR-9 agonists are considered among the most promising immunotherapeutic agents for breast cancer treatment." (PMID 41550509, 2026). "Due to a lack of TLR family immunohistochemical samples, only TLR3, TLR4, TLR7, and TLR8 staining results in colorectal cancer, breast cancer, prostate cancer, and normal tissue were exhibited, which were largely consistent with the previously reported mRNA expression." (PMID 35801728, 2022). "In fact, such a finding could in part be attributed to the promising antitumour effect of TLR-7 in various cancers, such as OSCC, breast cancer and lymphoma." (PMID 33008143, 2020). "There are also many TLR7 agonists attracting researchers' interest: SM-276001 and SM -360320 are selective TLR7 agonist, and SM-360320 can synergize with DNA vaccines targeting CEA colon cancer and HER2 breast cancer." (PMID 28620298, 2017). "Additionally, in breast cancer there are currently several clinical trials assessing efficacy of TLR7/8 agonists (TLR8, VTX-2337 and cyclophosphamide, NCT02650635; TLR7, imiquimod, cyclophosphamide, and radiotherapy)." (PMID 29190881, 2017). "The use of TLR7 agonists without additional delivery of DCs to the tumor was also investigated in a murine breast cancer model, showing that TLR7-triggering on infiltrating plasmacytoid DCs resulted in their activation." (PMID 25682197, 2015).
breast carcinoma (continued). "Also, the immunosuppressive activity and differentiation of MDSCs isolated from breast cancer patients were examined before and after targeting the STAT3 transcription factor using siRNA in MDSCs along with simultaneous activation of the TLR7/TLR8 signaling using a specific agonist." (PMID 33679700, 2020). "Our previous research demonstrated that IMQ- and CpG A-activated pDCs could kill breast cancer cells in vitro and inhibit breast tumor growth in vivo, at which IMQ was more effective than CpG A. However, the effect on pDCs of other TLR7 and TLR9 ligands is less well understood." (PMID 31093508, 2019).
rheumatoid arthritis (37 papers, 2009 to 2025). A chronic, systemic autoimmune disorder characterized by inflammation in the synovial membranes and articular surfaces. "TLR7 is widely distributed in immune cells, which can bind to MyD88 to initiate downstream inflammatory cascade responses, and is involved in rheumatoid arthritis progression." (PMID 38543188, 2024). "In rheumatoid arthritis, miR-574-5p promoted the maturation of osteoclasts and the development process of rheumatoid arthritis by binding to the activated TLR7/8 signaling pathway." (PMID 35733923, 2022). "Recently, TLR7 was determined to regulate osteoclastogenesis in rheumatoid arthritis via RANKL expression in synovial fibroblasts." (PMID 34414191, 2021). "TLR7 induced IL-1β production in synovial fibroblasts and M1-type macrophage from rheumatoid arthritis patients was also in an IRF5-dependent manner." (PMID 34950033, 2021). "Taken together, our data indicate EFL2’s therapeutic potential as a candidate for rheumatoid arthritis and other TLR7-dependent diseases." (PMID 34950033, 2021). "We previously reported the therapeutic effects of topical imiquimod, a known TLR7-dependent inducer of type I IFN responses in mouse models of rheumatoid arthritis 13 and its effect on neutrophil recruitment." (PMID 32104502, 2020). "Previous studies have shown that TLR7 is expressed in rheumatoid arthritis monocyte derived dendritic cells and fibroblasts." (PMID 32788627, 2020). "A number of TLR7 antagonists are in clinical trials for treatment of autoimmune and inflammatory diseases such as rheumatoid arthritis, colitis, and multiple sclerosis." (PMID 31511910, 2019). "Additionally, let-7b strongly stimulated TLR7-positive myeloid cells found within synovial fluid, driving their development toward pro-inflammatory M1 macrophages in a murine model of rheumatoid arthritis." (PMID 30455702, 2018). "Our studies have shown that the onset of rheumatoid arthritis (RA) is abrogated by the inhibition of IRAK4 in TLR7-induced inflammation in macrophage and fibroblast cell-based and in vivo models of joint inflammation." (PMID 40709261, 2025). "TLR7 agonists can be used as vaccine adjuvants or to boost anti‐tumour immunity, while antagonists may be beneficial in conditions such as systemic‐lupus erythematosus or rheumatoid arthritis, where TLR7 mediates the production of type I IFN." (PMID 31608988, 2020). "We focused on inflammatory bowel diseases (IBD) and rheumatoid arthritis (RA), two IMIDs with worldwide growing prevalence, as well as on the infectious COVID-19 disease, a recent major healthcare issue, and involving the TLR7/8 signaling pathways." (PMID 40208878, 2025). "Among them, IMO-3100, a TLR7/9 dual antagonist of TLR7 and TLR9 can block the expression of IFN-β, TNF-α, and interleukin 17 (IL-17) and attenuate SLE, rheumatoid arthritis (RA) in a murine model." (PMID 36677692, 2023). "TLR-7 has been shown to be involved in the pathogenesis of GD, while TLR-8 seems to be involved in the pathogenesis of rheumatoid arthritis." (PMID 37508529, 2023). "MiRs, being small ssRNA strands, have recently been documented as serving as ligands for TLR7 and TLR8, propagating such diseases as Alzheimer's disease, rheumatoid arthritis, and aGVHD." (PMID 30455702, 2018). "In patients with rheumatoid arthritis, the expression of TLR2, TLR3 and TLR7 is significantly enhanced in synovial fibroblasts." (PMID 24130907, 2013). "On the other hand, TLR-7/9 antagonists such as chloroquine, hydroxy-chloroquine and quinacrine have been widely used for the treatment of immune-mediated inflammatory disorders (herein, SLE, rheumatoid arthritis, and Sjögren’s syndrome)." (PMID 37508529, 2023). "Because of the ability of RP105 in blocking TLR2 and TLR7, it can be speculated that RP105 could regulate osteoclastogenesis in rheumatoid arthritis via a TLR2/TLR7." (PMID 34414191, 2021).
rheumatoid arthritis (continued). "Hence, the abnormal stimulation of TLR7 and TLR9 contributes to the pathology of autoimmune diseases such as SLE and rheumatoid arthritis (RA)." (PMID 34884569, 2021). "Moreover, TLR7 induces RANKL expression and increases osteoclasts derived from peripheral blood CD14 + monocytes in rheumatoid arthritis." (PMID 34414191, 2021). "At the same time, RP105 negatively regulates TLR7 and TLR9-mediated activation of macrophages and DCs via Lyn/SHP-1/2 signaling, suggesting a possible mechanism of osteoclastogenesis in patients with rheumatoid arthritis." (PMID 34414191, 2021). "In rheumatoid arthritis, osteoclast maturation is promoted by sEV‐derived miR‐574‐5p via the activation of TLR7/8 signalling without altering PGE2‐biosynthesis." (PMID 34596365, 2021). "All of these data suggest that IRAK-4 may be a suitable target for inflammatory diseases involving multiple receptors including IL-1R (rheumatoid arthritis (RA) and osteoarthritis (OA)), IL-18R (inflammatory bowel disease (IBD)), TLR2, 4 (RA), and TLR7, 9 (SLE)." (PMID 19689377, 2009). "For this purpose, we assessed the TLR7- and TLR9-mediated IFN-α production by pDCs in SLE patients and compared the finding with those in rheumatoid arthritis (RA) patients and healthy controls." (PMID 30210502, 2018).
HIV-1 infection (34 papers, 2009 to 2026). The type species of lentivirus and the etiologic agent of acquired immunodeficiency syndrome (AIDS). "The TLR7 rs179008 (A/T) polymorphism was associated with a worse prognosis during the course of HIV-1 infection; individuals with this polymorphism had greater viral loads and faster progression to immunosuppression." (PMID 39650644, 2024). "Women with acute HIV-1 infection carrying the TLR7 rs179008 (A/T) polymorphism had reduced viral load and lower frequency of clinical symptoms." (PMID 39650644, 2024). "The combination of TTA alleles for the TLR7 polymorphisms rs179010 (C/T), rs2074109 (T/C) and rs179009 (A/G) was associated with reduced susceptibility to HIV-1 infection, while the CTA haplotype was associated with the progression of chronic hepatitis B." (PMID 39650644, 2024). "Further, studies evaluating the associations of the TLR variant with the presence of HIV-1 infection showed that the TLR7 32A/T variant was more often detected in HIV-infected women compared to uninfected women." (PMID 37513727, 2023). "MSM patients were shown to have considerably lower frequencies of the TLR7 rs179010 allele T. Lower susceptibility to acute HIV-1 infection was linked to the haplotype TTA (patients with acute infections had slower disease progression and lower viral loads)." (PMID 36678440, 2023). "In the present review, the author will revisit the role of TLR7-driven pDC innate function in the context of HIV-1 infection to discuss at what stage of primary HIV-1 infection the TLR7 rs179008 T allele is likely to be protective in women." (PMID 34512664, 2021). "Here we show the associations between these intronic variations of TLR7 and the HIV-1 infection as well as the individual disease progression by adjusting viral load or set point in different clinical courses." (PMID 33193416, 2020). "We found that TLR7 rs179010 variation seems to be associated with acute stage of HIV-1 infection, while the variation of rs179009 was closely related to the chronic stage of HIV-1 infection." (PMID 33193416, 2020). "Further, a much lower frequency of this allele was present in patients with AHI-slow, indicating a potential effect of TLR7 rs179010 minor allele T against susceptibility and progression of the acute HIV-1 infection." (PMID 33193416, 2020). "In this study, we assessed the impact of three intronic SNPs of TLR7 on susceptibility to and disease progression of an HIV-1 infection in Chinese MSM." (PMID 33193416, 2020). "We evaluated the effect of TLR7 polymorphisms on disease susceptibility and progression of HIV-1 infection in Chinese MSM (men who have sex with men)." (PMID 33193416, 2020). "For instance, in a mouse model of HIV-1 infection, sustained TLR7 stimulation causes activation and disruption of the lymphoid system, leading to pathology and poor outcome." (PMID 23484159, 2013). "Another study assessed TLR7 and eight gene polymorphisms associated with susceptibility to HIV-1 infection and found that TLR8 polymorphisms could affect HIV-1 infection." (PMID 37298575, 2023). "We hypothesized these variations of TLR7 might influence the susceptibility to and progression of an HIV-1 infection." (PMID 33193416, 2020). "In the present study, we found an association of TLR7 rs179010 minor allele T with low viral load in the acute phase of HIV-1 infection, which might be related to IFNα production." (PMID 33193416, 2020). "Because the T allele of rs179008 pQTL affects TLR7 protein expression and in turn TLR7-driven production of type I IFNs by pDCs in women, but not in men, its direct contribution on the clinical parameters of HIV-1 infection at the initial/acute phase of the disease was investigated in women." (PMID 34512664, 2021). "The HIV-1 infection also triggers innate immune receptors, including Toll-like receptor 7 (TLR7) and TLR8." (PMID 40006894, 2025).
HIV-1 infection (continued). "TLR7 polymorphisms influence the susceptibility and progression of HIV-1 infection in Chinese men who have sex with men (MSM), suggesting an active role of TLR7 in HIV infection." (PMID 37298575, 2023). "In the context of HIV-1 infection, it is well-established that the frequency of pDCs producing IFN-α upon TLR7 stimulation is significantly higher in women than in men, correlating with clinical differences in the course of HIV-1 infection." (PMID 36814288, 2023). "In the present review, the author will revisit the role of TLR7-driven pDC innate function in the context of HIV-1 infection to discuss at what stage of primary HIV-1 infection." (PMID 34512664, 2021). "T allele expression was associated with a lower TLR7 protein synthesis, blunted production of IFN-α by pDCs upon TLR7 stimulation, and an unexpectedly lower viral load during primary HIV-1 infection in women." (PMID 34512664, 2021). "The frequency of pDCs producing IFN-α is significantly higher in women than in men upon TLR7 engagement, which correlates, during primary infection, with the clinical differences in the course of HIV-1 infection together with a greater expression of ISG." (PMID 34512664, 2021). "Plasmacytoid dendritic cells (pDCs) produce type I interferon (IFN-I) during HIV-1 infection in response to TLR7 stimulation." (PMID 34512664, 2021). "During HIV-1 infection, pDC-activating TLR7/9 agonists induce TIM-3 expression and subsequently result in the impairment of pDC function." (PMID 29597250, 2018). "Silencing the expression of ATG7 in plasmacytoid DCs in vitro leads to a significant decrease in IFNα production following HIV-1 infection, highlighting a crucial role for autophagy in mediating TLR7-IFN signaling." (PMID 30510929, 2018). "Although TLR7 and TLR3 are both explicitly expressed in pDCs, TLR7 plays a more important role in recognition of pathogenic nucleic acid and stimulation of IFN-I in response to HIV-1 infection." (PMID 29163506, 2017). "R848 prevented HIV-1 infection when added prior to, or at the same time as the virus, demonstrating that the block to infection is activated rapidly upon TLR7/8 activation and is capable of terminating the infection." (PMID 27905985, 2016). "Candidates for factors that induce IFN-I in HIV-1 infection include viral single-stranded RNA, which is recognized by TLR7/8, and bacterial molecules such as LPS, which is elevated in HIV-1 infection and is recognized by TLR4." (PMID 23437155, 2013). "TLR7 is known to be expressed in human CD4+ T cells during HIV-1 infection, but it is still unknown whether TLR7 expression is maintained in CD4+ T cells after ART." (PMID 37227774, 2023). "Indeed, pDCs are specialized in the production of IFN-I through TLR7 signaling and play an important role in bridging innate and adaptive immunity in the context of HIV-1 infection." (PMID 34512664, 2021). "The data suggest a strong effect of TLR7 rs179010 in the initial stages of an HIV-1 infection." (PMID 33193416, 2020). "In this study, we found that genetic variation of TLR7 plays an important role in HIV-1 infection." (PMID 33193416, 2020). "In HIV-1 infection, female plasmacytoid dendritic cells produced higher levels of IFNα after TLR7 stimulation than males and also had enhanced expression levels of all 13 IFNα subtypes and IFNβ following stimulation of TLR7 on peripheral blood mononuclear cells (PBMCs)." (PMID 29662485, 2018). "During HIV-1 infection, innate immunity activation via ssRNA TLR7 signaling due to intestinal bacterial translocation and/or co-infection may favor immune activation." (PMID 29423061, 2018). "Since HIV-1 infection is characterized by a strong inflammatory environment, tissue disruption, and upregulation of TLR7 in CD4+ T cells, we wondered whether the TLR7/IRF-5 pathway was involved in impairing memory CD4+ T cell homeostasis during HIV-1 infection." (PMID 37227774, 2023).